S1PR1 (sphingosine-1-phosphate receptor 1)
Description:
G protein-coupled receptor for the bioactive lysosphingolipid sphingosine 1-phosphate (S1P) that seems to be coupled to the G(i) subclass of heteromeric G proteins. Signaling leads to the activation of RAC1, SRC, PTK2/FAK1 and MAP kinases. Plays an important role in cell migration, probably via its role in the reorganization of the actin cytoskeleton and the formation of lamellipodia in response to stimuli that increase the activity of the sphingosine kinase SPHK1. Required for normal chemotaxis toward sphingosine 1-phosphate. Required for normal embryonic heart development and normal cardiac morphogenesis. Plays an important role in the regulation of sprouting angiogenesis and vascular maturation. Inhibits sprouting angiogenesis to prevent excessive sprouting during blood vessel development. Required for normal egress of mature T-cells from the thymus into the blood stream and into peripheral lymphoid organs. Plays a role in the migration of osteoclast precursor cells, the regulation of bone mineralization and bone homeostasis (By similarity). Plays a role in responses to oxidized 1-palmitoyl-2-arachidonoyl-sn-glycero-3-phosphocholine by pulmonary endothelial cells and in the protection against ventilator-induced lung injury.
Synonyms: S1P1; CD363; CHEDG1; EDG1; edg-1; D1S3362; ECGF1
Tractability: Small molecule: an approved drug acts on it; a structure with a bound ligand is known; a high-quality ligand is known; it belongs to a druggable protein family. Antibody: UniProt places it where antibodies can reach, with high confidence; its Gene Ontology location is reachable by antibodies, with high confidence; UniProt predicts a signal peptide or a membrane-spanning region. PROTAC: ubiquitination databases record sites on it; a small molecule that binds it is known.
Target class: EDG receptor; Family A G protein-coupled receptor; Lipid-like ligand receptor (family A GPCR); Membrane receptor; Small molecule receptor (family A GPCR)
Chemical probes: CHEMBL210352, CHEMBL377855, CYM5181 (high quality), SEW-2871 (high quality), W146
Gene: Protein-coding gene on chromosome 1 (101,235,366 to 101,243,713, forward strand). Ensembl gene ENSG00000170989.
Subcellular location: Cell membrane; Endosome; Membrane raft
Subcellular location (Human Protein Atlas): Vesicles
Pathways (Reactome):
Disease: Potential therapeutics for SARS
Immune System: Interleukin-4 and Interleukin-13 signaling
Signal Transduction: Lysosphingolipid and LPA receptors
Gene Ontology:
Molecular function: G protein-coupled receptor binding; protein binding; sphingosine-1-phosphate receptor activity; G protein-coupled receptor activity; sphingolipid binding
Biological process: sphingosine-1-phosphate receptor signaling pathway; T cell migration; actin cytoskeleton organization; adenylate cyclase-activating G protein-coupled receptor signaling pathway; angiogenesis; blood vessel maturation; cardiac muscle tissue growth involved in heart morphogenesis; cell adhesion; cell migration; chemotaxis; G protein-coupled receptor signaling pathway; heart trabecula morphogenesis; lamellipodium assembly; regulation of bone mineralization; regulation of bone resorption; adenylate cyclase-inhibiting G protein-coupled receptor signaling pathway; endothelial cell differentiation; negative regulation of stress fiber assembly; neuron differentiation; phospholipase C-activating G protein-coupled receptor signaling pathway; positive regulation of cell migration; positive regulation of positive chemotaxis; positive regulation of smooth muscle cell proliferation; positive regulation of transcription by RNA polymerase II; transmission of nerve impulse
Cellular component: plasma membrane; cytoplasm; endosome; external side of plasma membrane; membrane; membrane raft; presynapse
Genetic constraint (gnomAD): Loss-of-function variants: 2 observed, 19.57 expected, observed/expected ratio (o/e) 0.1, 90% interval 0.041 to 0.32. The upper end of that interval is the gene's LOEUF score, 0.32, which puts it in group 1 of 6, group 1 being the genes least tolerant of losing a copy. Missense variants: 335 observed, 526.62 expected, observed/expected ratio (o/e) 0.64, 90% interval 0.58 to 0.7. Synonymous variants: 222 observed, 226.67 expected, observed/expected ratio (o/e) 0.98, 90% interval 0.88 to 1.1.
Homologues: Orthologues: chimpanzee S1PR1 (99% identical), macaque S1PR1 (98% identical), pig S1PR1 (95% identical), mouse S1pr1 (94% identical), rat S1pr1 (93% identical), guinea pig S1PR1 (92% identical), rabbit S1PR1 (90% identical), dog S1PR1 (90% identical), tropical clawed frog s1pr1 (72% identical), zebrafish s1pr1 (67% identical). Paralogues in human: S1PR3 (49% identical), S1PR5 (45% identical), S1PR2 (43% identical), S1PR4 (36% identical), LPAR1 (33% identical), LPAR2 (31% identical), LPAR3 (29% identical), GPR12 (24% identical), CNR1 (23% identical), GPR6 (23% identical), MC5R (23% identical), CNR2 (22% identical), and 6 more.
Diseases named in the same sentence as S1PR1 in open-access papers:
S1PR1 is named in the same sentence as 273 diseases in open-access papers, as found by Europe PMC text mining. Sharing a sentence is not in itself a finding about the gene and the disease. The quoted sentences say what the papers report.
multiple sclerosis (79 papers, 2011 to 2025). A progressive autoimmune disorder affecting the central nervous system resulting in demyelination. "It is known to cause initial activation but then degradation of S1PR1 in lymphocytes, which is its mechanism of action in the treatment of multiple sclerosis." (PMID 35980492, 2022). "Overexpression of S1PR1 in T cells from the brain tissue of multiple sclerosis patients is associated with neuroinflammation 42; therefore, upregulation of S1PR1 in T cells of Lck-BPI Tg mice may be also involved in the development of neuroinflammation." (PMID 34815797, 2021). "Nearly a dozen FDA-approved drugs are used for inhibiting S1PR1 and treating a variety of autoimmune diseases, including multiple sclerosis and IBD." (PMID 40553105, 2025). "Among those are Ozanimod, an S1PR1/5 modulator approved for the treatment of ulcerative colitis and multiple sclerosis, and Etrasimod, an S1PR1/4/5 modulator approved for the treatment of ulcerative colitis." (PMID 40342995, 2025). "Inhibitors of S1PR1 are used to treat inflammatory diseases such as multiple sclerosis and IBD, which are diseases that are likely modulated by the lymphatic vasculature." (PMID 40553105, 2025). "S1PR1 is up-regulated in several autoimmune diseases such as multiple sclerosis, systemic lupus erythematosus or rheumatoid arthritis and agents which inhibit S1PR1 are being investigated for their therapeutic potential." (PMID 39691709, 2024). "The objective of this study was to examine the impact of specific S1PR1 SNPs on drug binding affinities, with the aim to support personalized treatment strategies for multiple sclerosis." (PMID 39598537, 2024). "Four drugs that target S1PR1 have been approved by the FDA to treat multiple sclerosis, and two have been approved to treat ulcerative colitis." (PMID 38194271, 2024). "This study establishes an important foundation for understanding how specific SNPs can alter drug binding affinities and interactions with the S1PR1, thereby paving the way for personalized treatment strategies in multiple sclerosis." (PMID 39598537, 2024). "S1PR1 inhibitors, such as siponimod and ponesimod, are already in clinical use for the treatment of multiple sclerosis, and there is potential for their application in modulating responses to CD20 antibody immunotherapy in lymphoma patients." (PMID 38339325, 2024). "S1PR1 modulators have had remarkable clinical efficacy treating multiple sclerosis and ulcerative colitis (UC)." (PMID 38194271, 2024). "This downregulation of S1PR1 and the consequent retention of lymphocytes within the lymph nodes has been exploited for the treatment of the relapsing and remitting form of multiple sclerosis, in order to alleviate autoimmunity symptoms." (PMID 36672428, 2023). "The development of fingolimod, an inverse agonist of S1PR1 for the treatment of multiple sclerosis was a successful application of the S1P signaling pharmacology." (PMID 37685894, 2023). "Fingolimod, a functional antagonist of S1PR1 and approved as an oral drug for treating relapsing forms of multiple sclerosis, has been reported to exhibit anticancer properties by inhibiting the S1PR1 signaling pathways in various types of cancer." (PMID 37220855, 2023). "Although the S1P and STAT3 signaling pathways are mostly reported in cancer research, a recent preclinical study of multiple sclerosis suggests that S1PR1 in microglia promotes the activation of downstream STAT3 signaling pathways in microglia." (PMID 35144528, 2022). "For instance, Fingolimod (FTY720), an agonist of S1PR1, is already in clinical use for multiple sclerosis (MS), a chronic autoimmune inflammatory disorder." (PMID 36121875, 2022). "S1PR1 has become a new target for the treatment of central nervous system diseases, including multiple sclerosis and Parkinson’s disease." (PMID 35144528, 2022). "And FTY720 is the first FDA-approved oral S1PR1 modulator which is beneficial for multiple sclerosis." (PMID 33390799, 2021).
multiple sclerosis (continued). "This downregulation of S1PR1 has been exploited for the treatment of multiple sclerosis using fingolimod." (PMID 32977496, 2020). "Most notably S1PR1 modulators (Fingolimod, MT-1303, Ozanimod) are tested or already in clinical use for treating inflammation-driven diseases such as multiple sclerosis, inflammatory bowel disease and psoriasis." (PMID 31379883, 2019). "It is flanked by S1PR1 and OLFM3 genes, and is 200 kb from a multiple sclerosis susceptibility gene." (PMID 24511991, 2014). "FTY720 has been recently FDA-approved for the treatment of multiple sclerosis and is postulated to exert its actions, at least in part, through the binding, internalization, and subsequent blockade of S1PR1 signaling." (PMID 23372844, 2013). "Modulators targeting S1PR1 are already FDA-approved therapeutics of treating multiple sclerosis, which could further accelerate its important role for treatment development in schizophrenia." (PMID 35350429, 2022). "Fingolimod is the first approved S1PR1 regulator and is used to treat multiple sclerosis." (PMID 36434688, 2022). "Additionally, S1PR1 radioligand has gained significant interest for in vivo targeted imaging of inflammation in brain diseases, with the recent FDA-approved S1PR1-based treatments such as Fingolimod, Siponimod, and Ozanimod for multiple sclerosis." (PMID 35350429, 2022). "The phosphorylated version of Fingolimod (pFTY720), an oral therapy for multiple sclerosis (MS), induces S1PR1 internalisation in T cells, subsequent insensitivity to S1P gradients and sequestering of these cells within lymphoid organs, thus limiting immune response." (PMID 24911000, 2014). "Thus, in an earlier study it was reported that FTY720, an antagonist of S1PR signaling that is already approved for the treatment of patients with multiple sclerosis, can inhibit S1PR1 expression, downregulate STAT3 activity, and inhibit the growth of DLBCL cells both in vitro and in vivo." (PMID 38339325, 2024). "Ample evidence of S1P’s role has been collected in experiments using mice with genetic loss of S1PR1 as well as in models that have downregulation of S1PR1 by using a functional antagonist of S1PR1, FTY720, which is an FDA-approved drug for treatment of multiple sclerosis." (PMID 24286034, 2013). "A number of the S1PR agonists like fingolimod (FTY720), siponimod, ponesimod and ozanimod are S1PR1 modulators, have been approved by FDA for various forms of multiple sclerosis." (PMID 39618500, 2024). "Pharmacological downregulation of S1PR1 prevents trafficking of autoreactive T cells and is an FDA-approved treatment for multiple sclerosis." (PMID 32118582, 2020). "Our data identify S1PR1 antagonists as potential therapeutics to mitigate opioid-induced dependence and support repurposing the S1PR1 functional antagonist FTY720, which is FDA-approved for multiple sclerosis, as an opioid adjunct." (PMID 33092620, 2020). "Accordingly, astrocytic S1PR1 and S1PR3 were upregulated in multiple sclerosis lesions." (PMID 37508508, 2023). "This is consistent with astrocyte’s S1PR1 being a nonimmunological CNS target for FTY720 effectively targeting multiple sclerosis." (PMID 35326420, 2022). "Our work supportsinvestigating S1PR1 antagonists as a clinical approach to mitigate opioid-induced adverseeffects and the repurposing of the functional S1PR1 antagonist FTY720, which is alreadyFDA-approved for multiple sclerosis, as an opioid adjunct." (PMID 34612709, 2021). "In March 2020, ozanimod capsules, agonists for S1PR1 and S1PR5, were approved for application in the treatment of relapsing forms of multiple sclerosis by the US FDA, involving clinically isolated syndrome, relapsing-remitting disease, and active secondary progressive disease in adults." (PMID 34751249, 2021). "S1PR1 is a target of fingolimod, an FDA-approved immunosuppressive drug for multiple sclerosis." (PMID 33206327, 2021).
multiple sclerosis (continued). "Studies in multiple sclerosis using fingolimod as a functional antagonist of S1PR1 have indicated that it does not alter BBB integrity nor change MMP-9 expression." (PMID 32977496, 2020). "In addition, expression of S1PR1 and S1PR3 is increased in reactive astrocytes in multiple sclerosis lesions and in cultured astrocytes under proinflammatory circumstances." (PMID 31861214, 2019). "Alterations in the expression levels of S1PR isoforms have been demonstrated in other pathological states for instance upregulation of S1PR1 and S1PR3 and downregulation of S1PR2 were reported in multiple sclerosis lesions and in experimental asthma, respectively." (PMID 28493876, 2017). "S1PR1 signaling can be blocked by an effective inhibitor, FTY720, which was developed as an immunosuppressant and is being used in the treatment of patients with multiple sclerosis." (PMID 25472725, 2014). "Furthermore, the existence of next‐generation S1PR1‐targeted agents like Ozanimod (Zeposia, Celgene) and Siponimod (Mayzent), FDA‐approved drugs for the treatment of multiple sclerosis, suggests promising avenues for further advancements in this field." (PMID 39126272, 2024). "S1P modulators such as ceralifimod (selective S1PR1 and S1PR5 modulator), GSK2018682 (selective S1PR-1 and S1PR-5 modulator), and amiselimod (MT-1303) (selective S1PR-1 modulator) have been developed by different drugs companies to treat patients with multiple sclerosis." (PMID 35805142, 2022). "Other S1P analogues exhibiting higher S1PR specificity than fingolimod (FTY720) include siponimod/BAF13 (a potent agonist of S1PR1 and S1PR5 but not of S1PR3), and RPC1063/ozanimod have entered phase III clinical trials for multiple sclerosis." (PMID 31861214, 2019).
breast cancer (49 papers, 2012 to 2026). A primary or metastatic malignant neoplasm involving the breast. "The TCGA database showed that overexpression of S1PR1 was associated with the poor survival of breast cancer patients in every stage." (PMID 34059068, 2021). "A recent investigation in breast cancer showed that S1PR1 causes the change of TAMs phenotype, promotes neo-lymph vascularization, and the change of TME via activating inflammatory factors such as Nlrp3 and IL-1β." (PMID 34283088, 2021). "In the current study, we demonstrated for the first time in human breast cancer that elevated inflammation was significantly associated with high expression of S1P-signaling genes, such as SphK1 and S1PR1." (PMID 33457427, 2020). "In agreement with our mechanistic model, we showed that human breast cancers with a high amount of angiogenesis are significantly associated with high expression of S1P-signaling genes, SphK1, S1PR1, and SPNS2." (PMID 32933189, 2020). "The down-regulation of S1PR1 was associated with worse prognosis in breast cancer and lung cancer and was significantly related to clinical characteristics, such as gender, population, smoking status, and stage." (PMID 32799825, 2020). "Given the elevated expression of IL-22R1 and S1PR1 in aggressive breast cancer, we analyzed the associations between the IL-22R1 and S1PR1 signatures and relapse free survival time in a cohort of 425 human breast cancer patients." (PMID 31935914, 2020). "Its determined that the low expression of S1PR1 is an independent risk factor for poor prognosis of breast cancer." (PMID 32799825, 2020). "In our study, S1PR1 was associated with two angiogenic patterns in breast cancer by regulating the RhoA signal pathway." (PMID 30814488, 2019). "In Nagahashi et al49 recent study, they used FTY720 to target SPHK1/S1P/S1PR1 axis and suggested that this pathway is associated with obesity‐related inflammation and breast cancer metastasis." (PMID 29923327, 2018). "Similarly, the administration of the S1PR1 antagonist FTY720 also alleviated bone loss in the breast cancer-bearing mice fed a high-fat diet." (PMID 42079390, 2026). "S1PR1 has been implicated in fostering migration, invasion, proliferation, and angiogenesis in an array of malignancies, including bladder cancer, esophageal cancer, ovarian cancer, renal cancer, colorectal cancer, breast cancer, and lung cancer." (PMID 39551792, 2024). "To investigate the association between breast cancer development and the IL-22 receptor, IL-22R1 and S1PR1 expression signatures, we compared the mRNA expression of IL-22R1 and S1PR1 in luminal and basal/triple-negative subtypes of breast cancer cell lines and breast tumors." (PMID 31935914, 2020). "Furthermore, we found that the IL-22R1 and S1PR1 mRNA levels are profoundly elevated and significantly associated with breast cancer tissues that have developed bone/brain metastasis." (PMID 31935914, 2020). "Notably, in three breast cancer cohorts (GSE1456-GPL96, GSE7378, and GSE12276), low S1PR1 expression was significantly associated with a poorer prognosis breast cancer." (PMID 32799825, 2020). "In addition, epidemiological data have shown that obesity is a risk factor for postmenopausal breast cancer and exacerbates cancer progression, and the upregulation of S1P/S1PR1/STAT3 signaling has also been implicated in a mouse model of breast cancer associated with obesity." (PMID 38542328, 2024). "Some of the alterations identified are drivers of different tumors and for VM formation: S1PR1 (breast cancer), PDGFRB, TIE-1 (melanoma), LOXL2 (hepatocellular carcinoma) and interestingly TCF-4." (PMID 36797281, 2023). "Overexpression of S1PR1 in breast cancer prevents the VM formation by inducing VE-cadherin phosphorylation on tyrosine 731, leading to disruption of the VE-cadherin/β-catenin complex and, thus, a reduction in tumor growth." (PMID 36835432, 2023).